MET (MET proto-oncogene, receptor tyrosine kinase)
Diseases named in the same sentence as MET in open-access papers (continued):
Sharing a sentence is not in itself a finding about the gene and the disease.
glioblastoma (continued). "In this study, we correlated glioblastoma locations with the expression of five mesenchymal genes (VEGFC and its receptor FLT4, HGF and its receptor MET, and CHI3L1) and five proneural genes (PROM1, NOTCH1, DLL3, PDGFRA, and BCAN)." (PMID 26637806, 2016). "In glioblastoma multiforme (GBM), the vascular endothelial growth factor (VEGF) suppresses tumor cell invasion by promoting the recruitment of protein tyrosine phosphatase 1B (PTP1B) to a complex formed by MET and VEGF receptor 2 (VEGFR2)." (PMID 39769452, 2024). "Moreover, the fusion of the MET sequence at its 5′ end with PTPRZ1 gene exons creates the PTPRZ1-MET fusion, which has been reported in brain cancers, including secondary glioblastomas and low-grade gliomas." (PMID 39598385, 2024). "A modulation of the tumor immune microenvironment in response to radiotherapy without or with MET inhibition in glioblastoma has not been studied." (PMID 36915128, 2023). "To test this prediction, we used a dual-guide CRISPR/enCas12a vector (see “Methods”) to knock out either CPD or negative control ADH7 in glioblastoma cell lines and examined MET protein." (PMID 35768873, 2022). "The immunosuppressive potency of the glioblastoma microenvironment may be a function of tumor invasiveness and epithelial-mesenchymal transition (EMT), in which c-MET plays a key role." (PMID 34532286, 2021). "Thus, the siRNA-mediated targeting of c-MET, a protein was shown to mediate tumor invasiveness in glioblastoma multiforme, was accomplished through cationic solid lipid nanoparticle formed from reconstituted LDL and complexed with pegylated-cMet-siRNA." (PMID 33594923, 2021). "Hence, c-MET is a robust actor of anti-angiogenic resistance by promoting EMT-like phenotype and invasiveness in glioblastoma." (PMID 32775327, 2020). "In bevacizumab-resistant glioblastomas, increased levels of CAIX and of c-MET were observed." (PMID 32775327, 2020). "Isolated reports of success with targeting tyrosine kinase inhibitors less frequently altered in glioblastoma (PDGFRA, FGFR, and c-MET) have also been reported, but clinical results have been inconsistent, likely due to mechanisms of resistance similar to those seen in the EGFRvIII trials." (PMID 33396284, 2020). "Indeed, while BMS-777607 is marketed as a c-MET inhibitor, one recent study utilized it to therapeutically target AXL in a model of glioblastoma." (PMID 30863365, 2019). "Hence, we screened a panel of cells lines representing renal cancer (CAKI‐1, CAKI‐2, ACHN), bladder cancer (UC13, T24), and glioblastoma (U87MG), for expression of SEMA3C, EGFR, MET, Plexin B1, Plexin D1, NRP1, and NRP2." (PMID 29348142, 2018). "Finally, based on signaling pathways activated in patients with low levels of RND1, we identified an RND1low signature of six genes (MET, LAMC1, ITGA5, COL5A1, COL3A1, COL1A2) that is an independent prognostic factor in glioblastoma." (PMID 30333910, 2018). "Increased MET expression and HGF-dependent invasion under hypoxia has been described years ago and has been subsequently confirmed by other studies conducted in several model systems, including glioblastoma and pancreatic cancer." (PMID 28445144, 2017). "Increased c-MET and TGF-β pathway activity may promote tumor progression in glioblastoma via invasion, migration, angiogenesis, cell survival, SC maintenance, and immune evasion, however, their potential interactions may not have been sufficiently studied." (PMID 29238047, 2017). "Despite the significant role attributed to transforming growth factor (TGF)-β family and hepatocyte growth factor (HGF)/c-MET signaling in glioblastoma pathogenesis, their functional interactions have not been well characterized." (PMID 29238047, 2017). "A novel multikinase inhibitor of MET, VERFR1, AXL, TIE2, KIT, FLT3, and RET, called cabozantinib (also known as XL184), inhibits the growth, metastasis, and angiogenesis in pancreatic cancer and glioblastoma, and reduces resistance to gemcitabine." (PMID 26225770, 2015).
glioblastoma (continued). "Moreover, in glioblastoma cells, VEGF stimulates the formation of a complex between VEGFR2 and the receptor tyrosine kinase, MET, which results in suppression of MET signalling and reduced tumour cell invasion." (PMID 24482243, 2014). "MET, the tyrosine kinase receptor of HGF, is another potential target in different types of solid and hematological neoplasms, such as colorectal carcinoma, glioblastoma, and breast carcinoma." (PMID 28548076, 2014). "PTEN status affected anti-c-MET therapies to glioblastomas in which PTEN protein expression was frequently low or absent, and combining anti-HGF/c-MET therapies with mTOR inhibitors additively inhibited growth of glioblastoma xenografts." (PMID 25098767, 2014). "The poor efficacy of single treatments may be explained by concurrent activation of multiple RTKs in glioblastoma, including EGFR, ERBB2, PDGFRA and MET." (PMID 23874926, 2013). "Our finding of simultaneous amplification of PDGFRA and MET in a subset of DIPG, for example, may justify the use of multikinase inhibitors or combinations of TKI, as has been demonstrated for pediatric glioblastoma cells in vitro." (PMID 22389665, 2012). "A new MET kinase inhibitor, PLB-1001, was applied in a Phase I clinical trial that enrolled MET-altered chemo-resistant glioma patients and achieved a partial response in at least two patients with advanced secondary glioblastoma without any significant side effects." (PMID 40469416, 2025). "However, MET inhibitors failed to prolong the survival of patients with glioblastoma in multiple clinical trials." (PMID 40469416, 2025). "Several reports of MET amplification–mediated resistance to targeted therapies have emerged thereafter, including to anaplastic lymphoma kinase (ALK) inhibitors in ALK-rearranged NSCLC, cetuximab in colorectal cancers, and antiangiogenic therapies in glioblastoma." (PMID 34516823, 2021). "In glioblastomas (GBM), the most common alterations were gene amplifications (PDGFRA, KIT, KDR, EGFR, and MET) and deletions (CDKN2A and PTEN)." (PMID 27172220, 2016). "Along with their ability to hamper HGF/MET signaling in a number of biochemical and biological assays, these antibodies displayed anti-tumor and/or anti-metastatic activity in preclinical models of HGF-dependent glioblastoma, triple-negative breast cancer, and colorectal cancer." (PMID 28548076, 2014). "Compensatory and redundant signaling is a characteristic of several cancer types, such as glioblastoma multiforme (GBM), wherein activation of PDGF, MET, and EGFR family members collectively limits the therapeutic efficacy of specific TKI agents." (PMID 20628489, 2010). "To determine the mechanism responsible for this reduced HGF/MET signaling in oval cells with C3G down-regulation, we search for a potential alteration in MET membrane localization and/or recycling as C3G facilitates recycling and membrane localization of EGFR in glioblastoma (GBM) cells." (PMID 36263169, 2022). "In vivo endothelial cell-specific knockout of MET (through the generation of Tie-Cre Metfl/fl mice) led to normalised vasculature, reduced intra-tumoural hypoxia, slowed glioblastoma growth and importantly, sensitised glioblastoma tumours to temozolomide treatment, prolonging mouse survival." (PMID 33526881, 2021). "MET/HGF-specific mAbs such as onartuzumab have been investigated, with no clear clinical benefit shown in glioblastoma patients." (PMID 39518074, 2024). "Although such mechanisms have not yet been described in GBM, the intrinsic plasticity of glioblastoma stem cells and the frequent activation of bypass pathways (e.g., EGFR, MET, PDGFR) suggest that resistance could also emerge in this context." (PMID 41002392, 2025).
glioblastoma (continued). "There was also an absence of MET amplification and FGFR3 fusion in the de novo RRD glioblastomas." (PMID 38079020, 2023). "No tumors demonstrated EGFR amplification, MET amplification, CDK4 amplification, MDM2 or MDM4 amplification, PTEN homozygous deletion, or NF1 homozygous deletion that are frequent oncogenic events in conventional IDH-wildtype glioblastomas." (PMID 38079020, 2023). "Furthermore, no BRAF and RAF1 fusions were found in glioblastoma, which are characterized by fusions with NTRK, FGFR, MET or ROS1." (PMID 35169893, 2022).
glioma (227 papers, 2010 to 2026). A benign or malignant brain and spinal cord tumor that arises from glial cells (astrocytes, oligodendrocytes, ependymal cells). "Activating mutations in MET are essential in the advancement of low-grade gliomas to secondary GBM, with MET amplification associated with reduced overall survival rates." (PMID 40332008, 2025). "High expression of c-MET was associated with poor survival among glioma patients from TCGA and CGGA." (PMID 38352883, 2024). "An RNA-seq investigation of 272 gliomas found fusion transcripts of the MET genes triggering mutations in other genes, including PTPRZ1-MET." (PMID 38201528, 2023). "PTPRZ1-MET fusion was reported to associate with glioma progression from low-grade to high-grade glioma, which was a target by a MET inhibitor vebreltinib." (PMID 37443050, 2023). "A mutated, constitutively active variant of MET, METΔ7−8, has been identified in 6% of patients with high grade gliomas, including GBM, enhancing downstream signalling to promote tumour progression and angiogenesis." (PMID 31616641, 2019). "One gene noteworthy is the PTPRZ1, which is a receptor tyrosine phosphatase recently found upregulated in a fusion transcript with the MET gene and associated to glioma progression." (PMID 29844869, 2018). "EGFR, PDGFRA, FGFR1, FGFR2, FGFR4 and MET are frequently amplified, mutated, or fused in high-grade gliomas or in secondary GBMs." (PMID 27385209, 2016). "The RMPAhigh gliomas were enriched in immature vessel cells and tumor associated macrophages, and both cell types expressed high levels of pro-angiogenic RTKs including MET, VEGFR1, KDR, EPHB4 and NRP1." (PMID 27385209, 2016). "The protooncogene MET (c-met) is amplified in human gliomas and causes increased activity of its downstream targets, resulting in enhanced proliferation, invasion, migration, angiogenesis and survival of malignant gliomas." (PMID 24213322, 2012). "Furthermore, the co‐occurrence of MET exon 14 and other fusions is linked to an increase in tumor‐associated macrophages, a factor associated with a poor prognosis in glioma patients." (PMID 41521799, 2026). "In addition, the activation mutation of MET is an important promoter of the transformation of from low-grade glioma to secondary glioblastoma." (PMID 35935338, 2022). "Aberrant c-MET activity, arising due to either gene mutation or amplification, has frequently been implicated in the development and progression of multiple human cancers, including high-grade gliomas." (PMID 28821904, 2018). "To be able to investigate tumour heterogeneity with respect to oncogene expression, we applied padlock probe rolling circle amplification to indentify EGFR, MET and the whole-exon deletion splice variants of these oncogenes that play a role in, among others, glioma and NSCLC1,5,16,29–31." (PMID 29728634, 2018). "MET gene encodes hepatocyte growth factor receptor (also known as scatter factor), which is thought to play an important role in the migration, invasion, drug resistance and recurrence of glioma cells, especially in radiation resistance, inhibition of angiogenesis and hypoxia." (PMID 35135556, 2022). "Immunohistochemical labeling revealed the presence of MET in tumor cells, blood vessels, and peri-necrotic areas of glioma specimens." (PMID 40332008, 2025). "HGF, released by neurons and blood vessels, facilitates glioma invasion and the chemotactic migration of MET-positive cells, while also acting as a chemokine for microglial infiltration in malignant gliomas." (PMID 40332008, 2025). "Receptor tyrosine kinase family member MET acts as a critical signaling hub, with aberrant activation driving glioma malignancy and therapeutic resistance." (PMID 40654157, 2025). "When we compared tissue sections from MET+ and MET- gliomas, we observed a strong expression of the glioma MES-like marker CD4456, and the abundance of hypoxic areas in MET+ tumors, confirming the mesenchymal character of these gliomas." (PMID 41339360, 2025).
glioma (continued). "Tumors harboring NTRK, ALK, ROS1 and MET fusions have been classified in WHO CNS 5 under the umbrella term infant-type hemispheric gliomas due to their hemispheric predominance (96.7% of fusions)." (PMID 38525424, 2024). "MET expression has moreover been shown to correlate with tumor grade in human gliomas and has repeatedly been shown to enhance MAP kinase pathway signaling in glial and glioneuronal tumors." (PMID 38902810, 2024). "Accumulating evidence highlights the significant involvement of MET in pivotal aspects of glioma cell biology, including tumor proliferation, growth, migration, invasion, angiogenesis, and stemness." (PMID 38334610, 2024). "Fusions with receptor tyrosine kinase genes (such as ALK, ROS1, NTRK, and MET) are highly prevalent and preclinical studies show promising results for kinase inhibitors for this glioma type." (PMID 39273062, 2024). "Through the co-culture of PBMC and glioma cells, our data showed that down-regulation of c-MET in Ln299 significantly decreased the activation of STAT3 and the expression level of PDL1 in this cell." (PMID 38352883, 2024). "Infant-type hemispheric glioma shows gene rearrangements of NTRK1/2/3 or ROS/ALK1/MET alterations, leading to fusion of any RTK having intracellular tyrosine kinase domain." (PMID 39440342, 2024). "Recently, the detection of the novel TRIM24::MET fusion in a particularly aggressive high-grade glial tumor in a neonate has been reported for the first time." (PMID 38902810, 2024). "Another notable gene rearrangement is between MET and PTPRZ1, a gene encoding a tyrosine phosphatase, prevalent in certain brain tumors like low-grade gliomas and pediatric glioblastomas." (PMID 38675409, 2024). "MET amplification has been associated with high levels of PD-L1 expression in NSCLC, gastric carcinoma, malignant melanoma, and glioma patients." (PMID 38892318, 2024). "MET fusions result in the upregulation of the mitogen-activated protein kinase (MAPK) signaling pathway, which is associated with aggressive glial tumors in vivo." (PMID 38334610, 2024). "Here we assessed the role of the MET pathway in the response to radiotherapy in vitro and in vivo in syngeneic mouse glioma models." (PMID 36915128, 2023). "We conclude that synergistic suppression of experimental syngeneic glioma growth by irradiation and MET inhibition requires MET expression in the tumor as well as an intact immune system." (PMID 36915128, 2023). "The paracrine HGF secretion from neurons greatly facilitated glioma cells’ growth and development and chemotactic invasion in MET-positive cells." (PMID 38201528, 2023). "The human MET proto-oncogene is present on chromosome 7q31, and HGF is located on chromosome 7q21.1; the evidence was reported that MET plays a crucial role in glioma cell biology functions such as proliferation, growth, migration, invasion, and stemness." (PMID 38201528, 2023). "If proven effective, this targeted multifaceted intervention protocol will be extended for more glioma patients as a protocol to evaluate the safety and efficacy of MET inhibitors." (PMID 37443050, 2023). "MET amplification is a common (22.9%) alteration in diffuse pediatric-type high-grade glioma, H3-wildtype and IDH-wildtype." (PMID 37214395, 2023). "MET is among the top three dysregulated receptor tyrosine kinases (RTKs) in glioma cells, along with EGFR and PDGFRA." (PMID 37214395, 2023). "Here we explored the therapeutic efficacy and potential modes of action of MET-targeted therapy combined with irradiation in syngeneic murine glioma models in vitro and in vivo." (PMID 36915128, 2023). "In some studies, it was reported that MET expression was found in cytoplasm and cell membrane using immunohistochemical staining, and strong MET expression was reported in tumor cells, blood vessels, and glioma sample tissues." (PMID 38201528, 2023).